VCAN (versican)
Diseases named in the same sentence as VCAN in open-access papers (continued):
Sharing a sentence is not in itself a finding about the gene and the disease.
sarcoidosis (2 papers, 2022 to 2025). Sarcoidosis is a multisystemic disorder of unknown cause characterized by the formation of immune granulomas in involved organs. "Given the role of versican in inflammation and immune regulation, it's plausible that this matrix regulator is involved in the pathogenesis of sarcoidosis." (PMID 40521183, 2025). "However, there is no study linking versican, a critical extracellular matrix regulator of immunity and inflammation, to any type of sarcoidosis." (PMID 40521183, 2025).
sarcoma (2 papers, 2008 to 2026). A usually aggressive malignant neoplasm of the soft tissue or bone. "Through a combination of genetic (silencing, overexpression) and pharmacological approaches, applied in both a chemically induced murine sarcoma model and several human STS cell lines, we demonstrate that ERK5 positively regulates VCAN expression." (PMID 41800245, 2026).
soft tissue sarcoma (2 papers, 2023 to 2026). A malignant neoplasm arising from muscle tissue, adipose tissue, blood vessels, fibrous tissue, or other supportive tissues excluding the bones. "Together, these findings uncover VCAN as a key effector in ERK5-driven tumorigenesis and highlight the ERK5/VCAN signaling axis as a promising therapeutic target in soft tissue sarcomas." (PMID 41800245, 2026).
triple-negative breast carcinoma (2 papers, 2024 to 2025). An invasive breast carcinoma which is negative for expression of estrogen receptor (ER), progesterone receptor (PR), and human epidermal growth factor receptor 2 (HER2). "Additionally, in triple-negative breast cancer, an association between VCAN and the localization of CD8+ T cells to the tumor stroma was recently reported, and the specific chondroitin sulfate–glycosaminoglycan (CS-GAG) sulfation patterning is important for regulating T cell trafficking." (PMID 40361362, 2025). "Using a library of primary triple-negative breast cancer tissues, we correlated CD8+ T-cell tumor contact with ECM composition and identified a proteoglycan, versican (VCAN), as a putative member of the immunologic barrier." (PMID 38517140, 2024).
viral diseases (2 papers, 2018 to 2021). "A mouse model of acute lung injury induced by polyinosine-polycytidylic acid to mimic a viral infection has shown accumulation of versican in the lung." (PMID 29728109, 2018). "For example, the increased accumulation of VCAN is reported in viral diseases." (PMID 34884641, 2021).
ameloblastoma (1 paper, 2022). The most common odontogenic tumor, arising from the epithelial component of the embryonic tooth and usually affecting the molar-ramus region of the mandible or maxilla. "The immunostaining of versican in ameloblastoma was most prominent in the parenchyma than the stroma (p < 0.001)." (PMID 36338393, 2022). "The versican expression was higher in DF than in ameloblastoma by RT-PCR; however, there was a similar pattern between ameloblastoma and DF in immunochemistry analysis." (PMID 36338393, 2022). "Indirect immunofluorescence detected the ADAMTS-1 and versican expression in cell lines derived from ameloblastoma." (PMID 36338393, 2022). "This study showed a distinct expression of ADAMTS-1 and versican in ameloblastoma and DF, with ADAMTS-1 protein higher expression observed in ameloblastoma and possibly cleaved versican." (PMID 36338393, 2022). "Our goal was to elucidate whether ADAMTS-1, a member of the metalloproteinase family, and versican are expressed in ameloblastoma and whether they are correlated with biological behavior in the tumor." (PMID 36338393, 2022). "However, in the immunolocalization analysis, ADAMTS-1 was expressed in ameloblastoma more than in DF and versican immunostaining obtained a similar pattern between ameloblastoma and DF." (PMID 36338393, 2022). "Thus, this study aimed to investigate the gene and protein expression of ADAMTS-1 and versican in ameloblastoma." (PMID 36338393, 2022). "Fifteen ameloblastoma and 6 DF samples showed expression of versican." (PMID 36338393, 2022). "ADAMTS-1 and versican were overexpressed in DF than ameloblastoma by RT-PCR." (PMID 36338393, 2022). "Based on this finding and the high expression of ADAMTS-1, protein in the ameloblastoma in the present study may suggest that this enzyme may participate in the tumor invasion mechanism of this neoplasia, especially for the degradation of the substrate (versican) in the ECM." (PMID 36338393, 2022). "In this pilot study, we hypothesized that ameloblastoma may express ADAMTS-1, which can contribute to locally invasive tumor, through the degradation of versican." (PMID 36338393, 2022). "Versican was not differentially expressed between ameloblastoma neoplastic cells and epithelial cells of DF." (PMID 36338393, 2022). "In the present study, 16 samples of ameloblastoma expressed versican genes, only 4 samples were not expressed by RT-PCR, but all samples of ameloblastoma expressed versican by immunochemistry." (PMID 36338393, 2022).
arteriopathy (1 paper, 2025). "The objective of this work was to investigate the distribution of different isoforms of versican in PAH, to explore proteolytic turnover mediated by ADAMTS proteases, and to localize binding partners of versican in PAH arteriopathy." (PMID 40219589, 2025).
Arthritis (1 paper, 2006). Inflammation of a joint. "Genes known to be involved in autoimmune response and arthritis, such as those encoding Galectin-3, Versican, and Socs3, were identified and validated by quantitative TaqMan RT-PCR analysis using independent blood samples." (PMID 16507131, 2006).
basal cell carcinoma (1 paper, 2025). A carcinoma involving the basal cells. "Three key genes, VCAN, COL4A1 and COL5A2, may be involved in multiple activated signalling pathways in basal cell carcinoma, and they are co-enriched in extracellular space, extracellular region and endoplasmic reticulum lumen, extracellular matrix." (PMID 40386063, 2025).
bladder tumor (1 paper, 2021). "One report revealed that bladder tumor cell-derived versican drives lung metastasis in a TAM dependent manner 68; however, the mechanism underlying CCL2 expression in TAMs via versican warrants additional investigation." (PMID 33391518, 2021).
bronchiectasis (1 paper, 2024). Segmental, irreversible dilation of the bronchial tree resulting in the accumulation of secretions which leads to obstruction. "In addition, versican encoded by VCAN in the blood of patients with bronchiectasis was detected, and it was determined that the concentration of versican increased." (PMID 38685004, 2024). "To reveal a potential role for VCAN in bronchiectasis, we examined the mRNA expression of VCAN in bronchiectasis peripheral blood and bronchiectasis lung tissues from patients at the First Affiliated Hospital of Guangxi Medical University by RNA sequencing." (PMID 38685004, 2024). "The concentration of VCAN protein in the serum of patients with bronchiectasis was higher than that in the normal control group (P < 0.05)." (PMID 38685004, 2024). "Through in vitro cell migration experiments, it was determined that versican can induce the migration of neutrophils, indicating that VCAN plays an important role in the occurrence and development of bronchiectasis." (PMID 38685004, 2024). "The expression of VCAN was increased in the bronchiectasis tissues and peripheral blood (n = 5) compared with the controls (n = 4)." (PMID 38685004, 2024). "The expression of VCAN in peripheral blood and bronchial tissues of bronchiectasis were obtained by transcriptome sequencing." (PMID 38685004, 2024). "To investigate the effect of exogenous versican on the invasive capacities of bronchiectasis neutrophils, we performed a transwell assay." (PMID 38685004, 2024). "The protocol included four groups: the healthy neutrophils group, healthy neutrophils + versican group, bronchiectasis neutrophils group, and bronchiectasis neutrophils + versican group." (PMID 38685004, 2024). "We observed that more neutrophils invaded the extracellular matrix gel in contrast with the control neutrophils, suggesting that the migration of bronchiectasis neutrophils is attributed to versican." (PMID 38685004, 2024). "This study investigated the overexpression of VCAN in bronchiectasis based on the sequencing of blood and tissue and the validation of clinical samples." (PMID 38685004, 2024). "We found VCAN was overexpressed in bronchiectasis; the area under the ROC curve for scatter plots of GSE97298, blood, and tissue; and RT-qPCR showed that VCAN was upregulated in bronchiectasis." (PMID 38685004, 2024). "The expression of VCAN was upregulated in the bronchiectasis group by sequencing analysis (P < 0.001)." (PMID 38685004, 2024). "Our findings indicate that VCAN may be involved in the development of bronchiectasis by increasing the migration of neutrophils and play an important role in bronchial pathogenesis." (PMID 38685004, 2024). "Therefore, we explore the expression of VCAN in bronchiectasis and reveal its molecular mechanism and biological characteristics." (PMID 38685004, 2024). "As expected, VCAN was overexpressed in bronchiectasis after integrated analysis." (PMID 38685004, 2024). "Both healthy individuals and patients with bronchiectasis have a significant chemotactic effect on neutrophils in peripheral blood, which proved that versican plays an important role in the occurrence and development of bronchiectasis by inducing the migration of neutrophils." (PMID 38685004, 2024). "The results indicated that the concentration of versican was upregulated in bronchiectasis." (PMID 38685004, 2024). "VCAN contributes to disease pathophysiology and may be a target for bronchiectasis treatment." (PMID 38685004, 2024). "In summary, our study confirms that the expression levels of VCAN mRNA and protein in patients with bronchiectasis are elevated, which may be involved in the occurrence and development of bronchiectasis by increasing the migration and infiltration of neutrophils." (PMID 38685004, 2024). "Therefore, VCAN may be a potential therapeutic target for bronchiectasis." (PMID 38685004, 2024).
bronchiectasis (continued). "Presently, the mechanism of action of Versican in bronchiectasis and its relationship with neutrophils have not been reported." (PMID 38685004, 2024). "Presently, the role of VCAN in bronchiectasis has not been reported." (PMID 38685004, 2024).
carcinosarcoma (1 paper, 2016). A malignant tumor composed of a mixture of carcinomatous and sarcomatous elements. "Previous findings showing the relationship between HER-2 and versican expression in carcinomas in mixed tumors and carcinosarcomas support this hypothesis." (PMID 27490467, 2016).
cerebral cavernous malformation (1 paper, 2021). A disorder characterized by malformations in the structure of the capillaries in the brain. "It was also recently shown that proteolysis of versican by ADAMTS-5 constitutes a downstream mechanisms of the cerebral cavernous malformations (CCM) pathogenesis." (PMID 33804223, 2021).
chorioamnionitis (1 paper, 2024). A morphologic finding indicating inflammation of the fetal sac membranes. "However, it is not clear whether inflammatory factors produced in chorioamnionitis facilitate VCAN cleavage through induction of ADAMTS accumulation in the interstitial tissue." (PMID 38461223, 2024).
chronic kidney disease (1 paper, 2014). Impairment of the renal function secondary to chronic kidney damage persisting for three or more months. "Versican is a large extracellular matrix proteoglycan whose role in chronic kidney disease (CKD) has only been described to a certain extent." (PMID 25354390, 2014).
chronic pancreatitis (1 paper, 2011). A chronic inflammatory process causing damage and fibrosis of the pancreatic parenchyma. "The IHC analysis of lumican, versican and Col14A1 confirmed their up-regulation in chronic pancreatitis and pancreatic adenocarcinoma, and provided additional insights on how they behave at cellular level in association with the diseases." (PMID 22132114, 2011).
cleft palate (1 paper, 2021). Cleft palate is a fissure type embryopathy that affects the soft and hard palate to varying degrees. "Development of animal models to investigate functional relevance of ADAMTS-9 and ADAMTS-20 as well as of versican has allowed determining that a defective versican cleavage by these proteases is related with a cleft palate phenotype." (PMID 33804223, 2021).
colon adenoma (1 paper, 2017). An adenoma that arises from the colon. "Lumican and versican expression were both observed in neoplastic cells and in the tumor stroma of colon adenomas and carcinomas." (PMID 28481899, 2017).
colorectal adenoma (1 paper, 2017). An adenoma that arises from the colon or rectum. "Distribution of versican staining according to histological and molecular characteristics of the colorectal adenoma and carcinoma samples." (PMID 28481899, 2017).
cyst (1 paper, 2021). A sac-like closed membranous structure that may be empty or contain fluid or amorphous material. "Therefore, our objective was to verify the expression of ADAMTS-1, versican and pEGFR in Periapical Granuloma (PG) and in the Radicular Cyst (RC) since they are the most common lesions of the periapex." (PMID 33676487, 2021).
diabetic cardiomyopathy (1 paper, 2026). Diabetic cardiomyopathy is a disorder of the heart muscle in people with diabetes. "Adeno‐associated virus‐delivered versican overexpression was sufficient to ameliorate cardiac dysfunction in a murine model of diabetic cardiomyopathy." (PMID 40459298, 2026). "Above all, a versican‐based therapeutic approach needs to be tested in animal models to examine if versican is a valid therapeutic target for diabetic cardiomyopathy." (PMID 40459298, 2026). "Subsequently, a diabetic cardiomyopathy (DbCM) mouse model was used to test the effect of versican on the heart in vivo." (PMID 40459298, 2026).
dilated cardiomyopathies (1 paper, 2023). "In patients with hypertrophic and dilated cardiomyopathies, we found elevated levels of versican and a positive correlation between versican and collagen mRNA in the heart, as well as increased cleavage of full-length protein." (PMID 38076279, 2023). "In patients with dilated cardiomyopathy, we found a 1.5-fold increase in versican mRNA expression, a 2.27-fold increase of collagen I mRNA, and a 2-fold upregulation of collagen III mRNA compared to control hearts." (PMID 38076279, 2023). "Finally, we analyzed the expression and spatial distribution of versican and the DPEAAE fragment in myocardial samples from hypertrophic and dilated cardiomyopathy patients." (PMID 38076279, 2023).
ductal in situ carcinomas (1 paper, 2014). "This study provided evidence that versican is strongly expressed in the perilesional stroma of a subclass of ductal in situ carcinomas and that the extension of versican immunostaining is statistically related to the high grade." (PMID 25140302, 2014).
embryonic carcinoma (1 paper, 2013). "Although regulation of versican expression is not well understood, it has been shown to be a target of Wnt signaling, regulated by the phosphatidylinositol 3-kinase (PI3K) pathway in human embryonic carcinoma cells." (PMID 24180670, 2013).
endometrial cancer (1 paper, 2020). Primary or metastatic malignant neoplasm involving the endometrium (mucous membrane that lines the endometrial cavity). "Higher expression of VCAN is connected with pathogenesis of peritoneal endometriosis and seems to be an indicator of poor prognosis endometrial cancer." (PMID 32575462, 2020).
fatty liver (1 paper, 2018). "To further determine which genes might play a significant role in the progression of fatty liver, we used real-time qPCR to detect the expression of 8 DEGs using clinical samples, including CD24, PZP, COL1A1, COL1A2, LUM, VCAN, THBS2 and EPHA3." (PMID 29769552, 2018).
focal segmental glomerulosclerosis (1 paper, 2012). A renal disorder characterized by sclerotic lesions in the glomeruli. "In rats with adriamycin-induced nephropathy, that mimics aspects of human MCD and focal-segmental glomerulosclerosis (FSGS), a 1.5 fold (p = 0.03) increase in versican mRNA as compared to controls was found at 21 days." (PMID 23024773, 2012).
gallbladder cancer (1 paper, 2025). "The VCAN, which is specifically expressed in the c0-cluster, was identified as overexpressed in myeloid-derived suppressor cells (MDSC) in a previous single-cell analysis study based on human gallbladder cancer." (PMID 39688793, 2025).
glomerular diseases (1 paper, 2012). "In an independent cohort of 74 biopsies of glomerular diseases renal RNA levels of versican isoforms V0 and V1, but not V2 and V3 correlated significantly with creatinine after a mean follow up time of 53 months." (PMID 23024773, 2012).
hyperphosphatemia (1 paper, 2014). Abnormally high level of phosphate in the blood. "Hyperphosphatemia also leads the activation of the Wnt/β-catenin signaling pathway by the translocation of β-catenin into the smooth muscle cell nucleus, increasing the expression of direct target genes such as cyclin D1, axin 2, and VCAN/versican." (PMID 25136676, 2014).
Hypoglycemia (1 paper, 2016). A decreased concentration of glucose in the blood. "Moreover, we were able to point out several glycoproteins (Fibulin1, Versican, Fibromodulin) linked to the extracellular matrix (ECM), many crystallins and few solute carriers (Slc26a4, Slc6a13) whose expression was modified by hypoglycemia." (PMID 26918849, 2016).
in situ carcinoma (1 paper, 2011). A malignant epithelial neoplasm which is confined to the epithelial layer without evidence of further tissue invasion. "Elevated levels of versican were correlated with higher tumor grade and invasiveness in carcinomas with MD and MAMCs, whereas increased amounts of decorin were associated with in situ carcinomas in MAMCs." (PMID 21791066, 2011).
infiltrating ductal carcinoma (1 paper, 2007). "Of interest is the observation that peripheral areas of infiltrating ductal carcinoma have intense versican expression." (PMID 17662123, 2007).
inflammatory bowel disease (1 paper, 2026). A spectrum of small and large bowel inflammatory diseases of unknown etiology. "In this work, we demonstrate CBP phosphorylation safeguards intestinal homeostasis by maintaining the stem cell niche through versican, highlighting versican as a potential therapeutic target for inflammatory bowel disease." (PMID 41904119, 2026).
insulinomas (1 paper, 2017). "Differential expression of UCH-L1, MAP1B, MAP2, VCAN, CDK4 and PDX-1 was verified in more than 40 PNETs, including insulinomas and non-insulinomas by IHC but the expression of CaSR was only validated in 29 insulinomas." (PMID 28526880, 2017).
Intraventricular hemorrhage (1 paper, 2023). Bleeding into the ventricles of the brain. "Similarly, there is an upregulation of aggrecan, brevican, neurocan and versican in rabbit pups after intraventricular hemorrhage." (PMID 38025264, 2023).
liver cirrhosis (1 paper, 2022). "The altered ECM landscape in liver cirrhosis include the upregulation of collagens (type I, III, IV, V, VI, VIII, X, XI, XII, XIV, XV, XVI, XVIII, XXI), proteoglycans such as versican, decorin, lumican, and glycoproteins including fibulins, fibronectin, and laminins (Dataset EV5)." (PMID 35579278, 2022).
lymphangioleiomyomatosis (1 paper, 2008). A multifocal neoplasm with perivascular epithelioid cell differentiation affecting almost exclusively females of child-bearing age. "In lymphangioleiomyomatosis (LAM), thickened alveolar walls and expanded interstitial tissues stain strongly for versican, as well as biglycan." (PMID 18485243, 2008). "A reciprocal relationship between versican and elastin and EBP has been previously demonstrated for vascular and dermal tissues, and also for the rare lung condition lymphangioleiomyomatosis." (PMID 18485243, 2008).